SLC26A4 (solute carrier family 26 member 4)
Diseases named in the same sentence as SLC26A4 in open-access papers (continued):
Sharing a sentence is not in itself a finding about the gene and the disease.
asthma (10 papers, 2017 to 2025). "This review aims to consolidate existing literature on the SLC gene family, with a specific focus on SLC26A4, elucidating its mechanisms of substrate transport and its associations with respiratory diseases, notably asthma." (PMID 39100210, 2024). "Elevated SLC26A4 expression has been linked to airway inflammation, hyperreactivity, and mucus production in asthma." (PMID 39100210, 2024). "Together, our study suggests that SLC26A4 may have the pathogenic significance in the development of asthma." (PMID 34101619, 2021). "To identify a novel mediator involved in asthma pathogenesis downstream of the IL-13 signals, we and others previously used DNA microarray to search for IL-13-induced molecules in human airway epithelial cells, finding that the SLC26A4 gene encoding pendrin is a downstream molecule of IL-13." (PMID 29359006, 2017). "While SLC26A4 inhibitors present potential treatments for asthma, further research is imperative to delineate their precise role in asthma pathogenesis and develop efficacious therapeutic strategies targeting this protein." (PMID 39100210, 2024). "It is possible that allergens can directly stimulate airway epithelial cells, leading to increased SLC26A4 expression as a part of the immune responses that contribute to airway inflammation and obstruction, and the exacerbation of asthma." (PMID 39100210, 2024). "Several inhibitors of SLC26A4 have been developed and found to be effective in suppressing airway hyperresponsiveness, airway inflammation, and some asthma-related phenotypes." (PMID 39100210, 2024). "Further studies on animal models provided supporting evidence that SLC26A4 is indeed expressed in the lungs of asthma model mice, including those induced by ovalbumin inhalation, IL-13 inhalation, and IL-13 transgenic mice." (PMID 39100210, 2024). "Overall, while the precise role of SLC26A4 in asthma requires further investigation, accumulating evidence suggests its involvement in the pathophysiology of inflammatory airway disease." (PMID 39100210, 2024). "Most importantly, SLC26A4 has been identified as a common mediator for mucus production in bronchial asthma, highlighting its significance in asthma characterized by mucus hypersecretion and airway obstruction." (PMID 39100210, 2024). "We explore triggers inducing SLC26A4 expression and its contributions to the pathogenesis of pulmonary diseases, particularly asthma." (PMID 39100210, 2024). "SLC26A4 is particularly relevant in the context of respiratory diseases such as asthma, where aberrant ion transport contributes to airway inflammation, hyperreactivity, and mucus hypersecretion." (PMID 39100210, 2024). "For example, SLC26A4 as one of the ion transports was reported to be increased in inflammatory lung diseases including asthma, COPD, and various infections." (PMID 39100210, 2024). "This positions SLC26A4 as a promising therapeutic target for asthma, where inhibition has been shown to enhance airway surface liquid volume and reduce airway hyperresponsiveness." (PMID 39100210, 2024). "While SLC26A4 expression is undetectable in normal airway epithelium, its expression is strongly up-regulated in inflammatory airway diseases such as asthma, allergic rhinitis, and COPD." (PMID 39100210, 2024). "SLC26A4 has been identified as a potential alternative therapeutic target for asthma exacerbations, and inhibition of SLC26A4 has been considered a validated approach to increase airway surface liquid volume, and attenuate airway hyperresponsiveness in asthma." (PMID 39100210, 2024). "Continued research is imperative to unravel SLC26A4’s intricate involvement and potential as a therapeutic target, especially considering its significant connections to respiratory disorders such as asthma." (PMID 39100210, 2024). "Consistent with the previous report, we found that SLC26A4 expression was increased in the lung tissues of patients with asthma." (PMID 34101619, 2021).
asthma (continued). "SLC26A4 has been implicated in the pathogenesis of COPD and asthma, including mucus hypersecretion, airway allergic inflammation, and airway hyperreactivity." (PMID 30654796, 2019). "SLC26A4 is another bronchial marker protein expressed in asthma and COPD, which has been suggested to contribute to mucin regulation." (PMID 29792201, 2018). "We and others previously found pendrin/SLC26A4 as a downstream molecule of IL-13, a signature type 2 cytokine critical for asthma, and showed its significance in the pathogenesis of asthma using model mice." (PMID 29359006, 2017). "Inhibition of SLC26A4 has shown promise in preclinical studies for attenuating airway hyperreactivity, reducing mucin expression, and dampening lung inflammation, highlighting its potential as a therapeutic target in asthma management." (PMID 39100210, 2024). "While the exact role of SLC26A4 regarding the pathogenesis of asthma is still unclear, our study suggests a novel mechanism that the RhoA-SLC26A4 axis in AT2 cells protects against allergic airway inflammation through the immuno-imbalance between augmented Treg and reduced ILC2 cells." (PMID 39100210, 2024). "By examining the current state of knowledge and identifying gaps in understanding, this review aims to stimulate further research into the role of SLC26A4 in asthma pathogenesis and the development of novel therapeutic interventions to alleviate asthma symptoms and improve patient outcomes." (PMID 39100210, 2024). "Thus, this study suggests an even broader role for SLC26A4 in the pathophysiology of asthma, especially considering its impact on ASL and its connection with allergic airway illness." (PMID 39100210, 2024). "Given that IL-17A is associated with severe asthma and neutrophil infiltration, it suggests that SLC26A4 expression might peak in patients with severe asthma." (PMID 39100210, 2024). "Additionally, the expression of SLC26A4 appears to be enhanced in both acute and chronic asthma models, indicating its potential involvement in the pathophysiology of asthma." (PMID 39100210, 2024). "SLC26A4 has been identified as a key mediator in regulating airway surface liquid thickness, mucus production, airway hyperresponsiveness, and inflammation in asthma." (PMID 39100210, 2024). "Furthermore, we explore how activated SLC26A4 is associated with various human diseases, including CRSwNP, COPD, asthma, cystic fibrosis, lung injury, hypertension, and renal acid-base homeostasis." (PMID 39100210, 2024). "However, translating these findings into clinical applications requires a deeper understanding of SLC26A4's precise role in asthma pathogenesis, as well as the development of efficacious and safe therapeutic strategies targeting this protein." (PMID 39100210, 2024). "However, the exact role of the anion transporter regarding the pathogenesis of asthma is still unclear, thus warranting further, in-depth investigations of SLC26A4 function in AT2 cells." (PMID 34101619, 2021). "Furthermore, the increased expression of SLC26A4 was also found in AT2 cells of our asthma mouse model as assessed by coimmunostaining of Slc26a4 and Sfptc." (PMID 34101619, 2021). "Of interest, SLC26A4 is increased in AT2 cells and serum of asthmatic patients and is associated with lung function, and inhibition of SLC26A4 promoted epithelial cell TGF-β1 release and attenuated allergic airway information in asthma." (PMID 34101619, 2021). "We and others previously found that pendrin/SLC26A4, an anion transporter located at the apical side of airway epithelial cells, is a downstream molecule of the IL-4/IL-13 signals that plays an important role in the pathogenesis of asthma." (PMID 29359006, 2017). "Thus, we used NPPB, an inhibitor of anion channels that has been shown to suppress Slc26a4-induced Cl– uptake and Slc26a4 activity, to explore whether Slc26a4 is a potential molecular target for asthma treatment." (PMID 34101619, 2021).
asthma (continued). "Importantly, our human study demonstrated that SLC26A4 expression was increased in AT2 cells of asthmatic patients, and demonstrated for the first time to our knowledge that serum levels of SLC26A4 were much higher in patients with mild and severe asthma compared with healthy controls." (PMID 34101619, 2021). "It would be of interest to explore the precise role of SLC26A4 in goblet cells and AT2 cells and investigate their impact on mucus production and pathology in asthma." (PMID 39100210, 2024). "While the role of SLC26A4 in asthma is not as well understood as in other conditions like hearing loss and thyroid disorders, emerging research suggests its involvement in airway inflammation and mucus production." (PMID 39100210, 2024). "Slc26a4/pendrin regulates HCO3- efflux following cytokine stimulation, which enhances Cl- secretion via CFTR, thereby impacting fluid and mucus homeostasis and was found upregulated in asthma and COPD15,16." (PMID 35842487, 2022). "Collectively, these results suggest an increased SLC26a4 in AT2 cells and serum of asthmatic patients, which may be critical in asthma." (PMID 34101619, 2021). "YS-01 (2-(4-(tert-butyl)phenyl)-4-(thiophen-2-ylmethylene)oxazol-5(4H)-one), a novel SLC26A4 inhibitor identified by the high-throughput screening of 54,400 synthetic compounds, showed strong therapeutic effects on allergic inflammation in a mouse model of OVA-induced asthma." (PMID 39100210, 2024). "Furthermore, the epithelial anion transporter SLC26A4 is induced by the combined effects of rhinovirus and IFN-γ during virus infection, regulates airway surface liquid (ASL) thickness, and increases airway reactivity and inflammation in an asthma model." (PMID 39100210, 2024).
thyroid cancer (10 papers, 2014 to 2025). "In addition, this may be in relation to what has been reported in humans harboring variants in genes implicated in TH synthesis (NIS, TG, TPO, and SLC26A4); thyroid goiter with dyshormonogenesis may develop thyroid cancer later in life." (PMID 37964961, 2023). "Hypermethylation of SLC26A4 often occurs in cancers such as thyroid cancer and acute myoid leukemia, consistent with our results." (PMID 35836192, 2022). "Moreover, it was shown that cell-free DNA, which has been suggested for cancer diagnosis and progression, of SLC26A4 is hypermethylated in blood of thyroid cancer patients." (PMID 38673775, 2024). "Furthermore, SLC26A4, which was also downregulated in PTC (log2FC = −3.31× 10−1; adjusted p-value = 8.84 × 10−9), has been implicated in thyroid cancer pathogenesis." (PMID 39408960, 2024). "In addition, analysis of gene expression patterns showed that SLC26A4 expression was downregulated in patients with prostate and thyroid cancers." (PMID 38673775, 2024). "SLC26A4 (Pendrin) exhibits reduced expression levels in thyroid cancers." (PMID 24795638, 2014). "The expression levels of CHEK1, c-KIT, SLC26A4, TG and TPO were significantly altered in all types of thyroid carcinomas." (PMID 27329729, 2016).
enlarged vestibular aqueduct syndrome (8 papers, 2010 to 2024). "An increasing number of biological and epidemiological evidence suggests that c.919-2A > G and c.2168A > G variants of solute carrier family 26, member 4 (SLC26A4) gene play a critical role in the development of large vestibular aqueduct syndrome (LVAS)." (PMID 32930899, 2020). "About 80% of large vestibular aqueduct syndrome patients have been found to harbor SLC26A4 c.919-2A>G mutations." (PMID 29634755, 2018). "In patients with enlarged vestibular aqueduct syndrome, both single heterozygous genes SLC26A4 (MIM*605646) and KCNJ10 (MIM*602208) induced the hearing loss in these patients." (PMID 21935370, 2011).
nonsyndromic hearing loss (8 papers, 2011 to 2022). "Although hundreds of genes have been reported to be associated with nonsyndromic hearing loss (NSHL), GJB2, GJB6, SLC26A4, and mitochondrial (mt) MT-RNR1 and MTTS are the major contributors." (PMID 28273078, 2017). "Although hundreds of genes have been reported to be associated with nonsyndromic hearing loss, GJB2, SLC26A4, and mtDNA12SrRNA are the major contributors." (PMID 27247933, 2016). "As for genetic factors of nonsyndromic deafness in China, the average value of variant in GJB2 seems to be the most common (23.37%), followed by SLC26A4 (14.74%), mtDNA 12SrRNA A1555G ( 2.44%), GJB3 (1.97%) and GJB6 (1.33%) genes." (PMID 23554706, 2011).
thyroid (7 papers, 2015 to 2026). "Co-expression analysis suggests interactions between SGIP1 and SLC26A4, implicating diverse pathways in thyroid carcinogenesis and informing precision medicine strategies." (PMID 42306204, 2026). "SLC26A4 is a key protein that transports iodine into the follicle to synthesize thyroid hormones, and its low expression is an early event in thyroid tumorigenesis." (PMID 36465624, 2022). "Until recently, there was no known correlation of specific mutations or variants of SLC26A4 with the presence or absence of the PS thyroid phenotype." (PMID 31266487, 2019).
cystic fibrosis (6 papers, 2019 to 2024). Autosomal recessive disorder caused by pathogenic variants in the CFTR gene (cystic fibrosis transmembrane conductance regulator), which encodes a chloride and bicarbonate channel expressed in epithelial cells, and follow the diagnosis criteria. "In particular, the ion transport of SLC26A4 is different from that of cystic fibrosis transmembrane conductance regulator (CFTR) in various organs and tissues, including the lung, kidney, thyroid, inner ear, parotid duct, and liver." (PMID 38673775, 2024). "SLC26A4 is also overexpressed in lungs affected by COPD, Bordetella pertussis infection, cystic fibrosis, and rhinovirus infection, and is associated with lipopolysaccharide (LPS)-induced acute lung injury." (PMID 39100210, 2024). "Additionally, based on their possible roles in anion transport, some members of the family, including SLC26A4 and SLC26A9, have been linked to cystic fibrosis as disease modifiers or potential therapeutic targets." (PMID 35204703, 2022).
Mondini dysplasia (6 papers, 2011 to 2024). "IP type II (IP-II), also known as Mondini dysplasia, is generally accompanied by an enlargement of the vestibular aqueduct and is primarily attributed to mutations in the SLC26A4 gene." (PMID 38742227, 2024). "Amongst them, 19 patients carrying bi-allelic SLC26A4 mutations were all confirmed to have inner ear malformation by CT scan including four cases of enlarged vestibular aqueduct (EVA) and 15 cases of Mondini dysplasia (MD)." (PMID 30842343, 2019).
thyroid dyshormonogenesis (6 papers, 2018 to 2025). "Genetic analysis via next generation sequencing (NGS) was performed finding two mutations associated with thyroid dyshormonogenesis: c.7813 C > T, homozygous in the exon 45 of the thyroglobulin gene (TG) and c.1682 G > A heterozygous in exon 15 of the SLC26A4 gene (pendrin)." (PMID 34063177, 2021).
Vertigo (6 papers, 2011 to 2025). An abnormal sensation of spinning while the body is actually stationary. "Patients with bi-allelic SLC26A4 variants often suffer from fluctuating hearing loss and recurrent vertigo, ultimately leading to severe to profound hearing impairment." (PMID 40507794, 2025). "The typical clinical characteristics of patients with EVA caused by biallelic SLC26A4 variants include fluctuating and progressive HL, often associated with vertigo and/or goiter." (PMID 38720048, 2024). "VL appeared to be independent also from most clinical characteristics, namely, age, gender, the presence of SLC26A4 mutation, the surgical approach, electrode type, perioperative gusher or post operative vertigo." (PMID 36825951, 2023). "Otherwise, the VL prevalence was not significantly different when weighted on age at intervention, gender, post-operative vertigo, gusher, CI model, surgical approach, presence of SLC26A4 mutation and bilateral/unilateral surgery." (PMID 36825951, 2023). "In comparison to hearing loss, less is known concerning the vestibular dysfunction associated with SLC26A4 mutations, despite the fact that as many as 70% of patients with SLC26A4 mutations suffer from episodes of vertigo." (PMID 21811566, 2011). "Among patients with SLC26A4 variants, out of the 11 patients with vestibular symptoms, eight patients (72.7%) complained of episodic vertigo, one patient (9.1%) complained of episodic vertigo and chronic dizziness, and two patients (18.2%) complained of occasional dizziness." (PMID 38720048, 2024). "Second, a significant proportion of mutant mice revealed severely impaired vestibular function, but patients with SLC26A4 mutations usually do not complain of vestibular symptoms, except during attacks of vertigo." (PMID 21811566, 2011).
CHARGE syndrome (5 papers, 2014 to 2025). CHARGE syndrome is a multiple congenital anomaly syndrome characterized by the variable combination of multiple anomalies, mainly Coloboma; Choanal atresia/stenosis; Cranial nerve dysfunction; Characteristic ear anomalies (known as the major 4 C's). "The most frequent genetic findings were SLC26A4 mutations and CHARGE syndrome (n = 4 each, 4.9%)." (PMID 41303275, 2025). "Furthermore, enlarged vestibular aqueduct, incomplete partition type III, lateral canal dysplasia as a manifestation of CHARGE syndrome was a very highly penetrant feature of mutations in SLC26A4, POU3F4, and CHD7, respectively in this population." (PMID 25373420, 2014). "Beyond anatomy, syndromic conditions and genetic variants, such as SLC26A4 mutations in EVA or CHARGE syndrome, as well as congenital infections including cytomegalovirus and Zika virus, may further compromise cochlear development and negatively impact implant performance." (PMID 41303275, 2025).
congenital hypothyroidism (5 papers, 2016 to 2025). A thyroid hormone deficiency present from birth. "This study provides novel insights into SLC26A4-related disorders in a Sudanese cohort with congenital hypothyroidism, integrating detailed clinical, biochemical, and molecular analyses." (PMID 40956475, 2025).
ear malformation (5 papers, 2014 to 2024). "SLC26A4 mutations are strongly associated with inner ear malformation and EVA." (PMID 30693673, 2019). "Also, the bi-allelic pathogenic mutations of SLC26A4 are more likely to induce inner ear malformation than single allele pathogenic mutation." (PMID 30842343, 2019).
high blood pressure (4 papers, 2018 to 2024). "Further studies demonstrated that SLC26A4 mutations protect against the development of high blood pressure through enhanced urinary Na+/Cl− excretion, suggesting that SLC26A4 can serve as a potential target for anti-hypertensive drugs." (PMID 39100210, 2024). "The loss of function of SLC26A4 in mice prevents development of bronchial asthma and hypertension symptoms; there is a possibility that mutations in the SLC26A4 gene among humans is a factor in the absence of these diseases." (PMID 29504915, 2018). "It is assumed that mutations in the SLC26A4 gene can impact the pathogenesis of bronchial asthma and hypertension and, as such, the comorbidity of these diseases." (PMID 29504915, 2018). "It was also reported that pendrin may regulate blood pressure because patients with SLC26A4 mutation are likely to be resistant to high blood pressure." (PMID 35154281, 2022). "More importantly, recent research found that SLC26A4 is associated with hypertension and left ventricular hypertrophy index is significantly reduced in patients with SLC26A4 mutation, indicating that SLC26A4-AS1 might participate in the processes of cardiac hypertrophy." (PMID 31998553, 2020).